GDF15 (growth differentiation factor 15)
Diseases named in the same sentence as GDF15 in open-access papers (continued):
Sharing a sentence is not in itself a finding about the gene and the disease.
cancer (continued). "Our data support the involvement of GDF-15 in the pathogenesis of cancer anorexia." (PMID 33396237, 2020). "It would be interesting to determine whether high levels of NF90 in HCC may have a role in promoting expression of GDF15 from liver cells in cancer patients." (PMID 32427329, 2020). "GDF15 reproducibly increases survival and reduces cancer growth of PCa prone transgenic TRAMP mice." (PMID 32502202, 2020). "There is considerable epidemiological data linking GDF15 to cancers." (PMID 32502202, 2020). "In the normal human body, the expression of GDF15 shows obvious tissue specificity, mainly distributed in the prostate, kidney and pancreas, whereas its expression was increased at the lesions of kidney and liver and in several cancers." (PMID 33098235, 2020). "Imaging markers may thus be better than plasma GDF-15 in detecting early disease since the elevation of GDF-15 seems to occur prior to cancer development." (PMID 30645608, 2019). "Although these studies have suggested that increased GDF15 expression may mediate aggressive cancer cell behaviors, little is known about its potential to induce cancer transformation of normal epithelial cells." (PMID 31389184, 2019). "Circulating GDF‐15 levels correlated significantly with other established cardiovascular biomarkers and inflammatory status in treatment‐naïve cancer patients in line with the proposed presence of a subclinical myocardial involvement with worsening disease severity." (PMID 31463975, 2019). "In addition, GDF15 is known to be highly expressed in placenta trophoblasts and many cancers, likely contribute to anorexia in pregnant women and cancer patients, respectively." (PMID 31535977, 2019). "Previous studies have hypothesized that GDF-15 could be used to assist the prediction of cancer recurrence and metastasis in CRC." (PMID 30808336, 2019). "Previous reports have identified an increase in plasma GDF-15 from healthy controls to cancer." (PMID 30645608, 2019). "It is known that GDF-15 can induce various pleiotropic effects during cancer progression by negatively or positively modulating cell proliferation, differentiation, apoptosis, invasion, and metastases, dependent of cancer cell types, disease stage, and tumor microenvironment." (PMID 30645608, 2019). "GDF-15 plays a very important and diverse function in cancer processes." (PMID 29467963, 2018). "In cancer, the cognitive receptor for GDF-15 is unknown; however, the C-terminal fragment of ANGPTL4, used in this study, can bind and activate β1 and β5 integrins, which could aid invasion." (PMID 30458137, 2018). "Many studies also consider that GDF15 is a contributor to the development and progression of some malignant tumors, although several documents have reported that retinoid-related molecule or anti-inflammatory drug can induce tumor cell apoptosis via GDF15." (PMID 29773900, 2018). "As cancer progresses, tumor cell resistance to GDF-15 and its elevated synthesis increases." (PMID 29467963, 2018). "Blood levels of growth differentiation factor-15 (GDF-15), also known as macrophage inhibitory cytokine-1 (MIC-1), have been associated with various pathological processes and diseases, including cardiovascular disease and cancer." (PMID 29628937, 2018). "Several studies showed that higher expression of GDF15 mRNA and protein in cancer biopsy samples." (PMID 30542297, 2018). "Overexpression of GDF15 prolonged survival and restrained cancer growth in TRAMP mice." (PMID 30542297, 2018). "This discrepancy may be due to the tumor suppressor activity of GDF15 in early stages of tumor development and progression and later becoming a tumor promoter as the tumor progresses into a malignant tumor." (PMID 30542297, 2018). "The biological roles of GDF15 have been investigated restrictively in cancer cells." (PMID 29724997, 2018).
cancer (continued). "However, recent studies have reported that GDF15 is highly expressed in many types of cancer tissues, including colorectal, gastric, esophageal, oral, pancreatic and so on." (PMID 29566722, 2018). "Although GDF15 has been shown to promote cancer cell death, whether it controls fibroblast proliferation and activation is unclear." (PMID 29724997, 2018). "Besides, growth differentiation factor 15 (GDF15) also tends to be an oncoprotein contributing to cancer cell proliferation." (PMID 29773900, 2018). "After reviewing the literatures on cytokine functions, we determined two candidates as fibroblast-inhibiting cytokines: cystatin C (CST3) has been reported to inhibit fibrosis by antagonizing TGF-β;22,23 growth differentiation factor 15 (GDF15) to induce cancer cell death." (PMID 29724997, 2018). "GDF15 is weakly and stably expressed in most tissues under normal physiological conditions but is substantially up-regulated under pathological conditions such as injury, inflammation and carcinoma, among other diseases." (PMID 29636108, 2018). "Recently, GDF15 was reported to have an important function in various types of carcinomas." (PMID 29636108, 2018). "Recently, several studies have reported that GDF15 is dysregulated in cancers." (PMID 27903972, 2017). "We further examined whether the ROS-cancer stemness regulatory axis can be modulated by GDF15, by using spheroid cell formation assays." (PMID 27903972, 2017). "Taken together, our results showed that GDF15 contributed to HNC by facilitating cancer stemness." (PMID 27903972, 2017). "We further examined whether GDF15 contributed to ROS suppression and cancer stemness through the SMAD regulatory pathway." (PMID 27903972, 2017). "As radioresistance is a characteristic of cancer stem cells, we examined whether GDF15 also plays a role in cancer stemness." (PMID 27903972, 2017). "In addition, the serum GDF-15 levels in human cancer patients are high, with declining patient survival." (PMID 28489602, 2017). "Thus, GDF15 contributes to radioresistance and cancer stemness in HNC through mechanisms involving in the inhibition of cellular ROS production." (PMID 27903972, 2017). "In support of this hypothesis, the TGF-β pathway has previously been reported to possess similar functions to those we found in GDF15, as promoting the radioresistant phenotype, reducing intracellular ROS level, and contributing to cancer stemness." (PMID 27903972, 2017). "Additionally, the cancer stemness phenotype promoted by GDF15 was significantly inhibited in SMAD1 knockdown cells, as shown in two HNC cell lines." (PMID 27903972, 2017). "Thirdly, GDF-15 can have pro- or antiproliferative properties in different settings of cancer." (PMID 29180833, 2017). "However, this reduction was rescued following rhGDF15 administration, with an approximately 2-fold increase in the two HNC cell lines, indicating that GDF15 can reverse the effects of ROS in the suppression of cancer stemness." (PMID 27903972, 2017). "We hypothesize that GDF15high cancer stem-like cells gain high proliferating activity by using the highly active GDF15 circuits in these cancer tissues." (PMID 28206960, 2017). "It was showed that GDF15 can be seen as prognostication of cancer morbidity and mortality in men." (PMID 26932592, 2016). "Several studies have reported GDF15 having various roles in cancer progression." (PMID 26892343, 2016). "GDF15 overexpression has been reported in several type of cancers, including OSCC." (PMID 26544895, 2016). "The number of selected genes by semi-supervised learning method is less than the single Cox and AFT model, but includes some genes which are significantly associated with cancer and cannot be selected by the two single Cox and AFT models, such as GDF15, ARHGDIB and PDGFRL." (PMID 26932592, 2016).
cancer (continued). "Understanding the GDF15 function in OSCC might be useful for identification of novel therapeutic targets and, ultimately, the personalization of cancer treatment based on the GDF15 mutations." (PMID 26544895, 2016). "In endometrial, prostate, pancreatic, and colorectal cancers, the circulating levels of GDF15 were elevated, which may correlate with poor clinical outcomes." (PMID 26497212, 2016). "Additionally, a study originally designed to evaluate GDF-15 for prognostication of cardiovascular and cancer morbidity and mortality in 940 older men reported a close association between the highest GDF-15 tertile and decline in renal function." (PMID 25944976, 2015). "The most parsimonious explanation that may explain these contradictions is that MIC-1/GDF15 regulates anti-cancer immunity, which in turn regulates cancer growth." (PMID 25695521, 2015). "There are many contradictory results with regard to the role of GDF15 in cancer cells." (PMID 23799024, 2013). "The objective was to evaluate the hypothesis that growth-differentiation factor 15 (GDF-15) is an independent marker of the long-term risk for both cardiovascular disease and cancer morbidity beyond clinical and biochemical risk factors." (PMID 24312445, 2013). "Recently several studies have found GDF-15 prognostic for long-term cardiovascular and non-cardiovascular mortality in healthy subjects without previous CVD, and in one of these studies, a high GDF-15 level was related to both cardiovascular and cancer mortality." (PMID 24312445, 2013). "Many patients with different types of cancers have elevated circulating levels of MIC-1/GDF15." (PMID 23468844, 2013). "The GDF-15 serum level also significantly increases in diverse aggressive human cancers." (PMID 24236027, 2013). "Cathepsin-S has recently been found associated with both cardiovascular and cancer mortality in the present cohort, although not including adjustment for biomarkers including troponin T and NT-proBNP and GDF-15." (PMID 24312445, 2013). "The association between GDF-15 was the only independent biomarker for cardiovascular and cancer morbidity and mortality in subjects without the respective diseases at baseline." (PMID 24312445, 2013). "MIC-1/GDF15 serum levels may rise because of the physiological factors such as increasing age or pregnancy, production by the cancer, cancer treatment, injury or intercurrent diseases." (PMID 22952779, 2012). "Because MIC-1/GDF15 is so frequently and substantially overexpressed in cancers, and because anti-cancer treatments induce MIC-1/GDF15 expression both in cancer and non-cancer tissues, any effects on tumor behavior may be of high clinical significance." (PMID 22952779, 2012). "In addition, we identified a panel of important cancer-related genes, which were differentially expressed upon GDF15 stimulation." (PMID 21625435, 2011). "Recent studies suggest that GDF15 might be involved in cell survival, cancer cell invasiveness, tumor-induced anorexia and weight loss." (PMID 21625435, 2011). "The current belief is that GDF15 has pleiotropic effects in cancer progression by functioning as a tumour suppressor inhibiting tumour growth, inducing apoptosis in early stages, although it promotes proliferation, migration, invasion and metastasis in more advanced disease stages." (PMID 21468045, 2011). "Next, we grouped them into cytokines associated with pre-cancer or the initiation stage of HCC (IL-6, TGF-β, MCP-1, FGF2, IL-2, IL-8, IL-12p40, IL-12p70, IL-18, IP-10, TNF-α, and IFN-γ), the early stage of HCC (OPN, GDF-15, RANTES, and VEGFA), and the advanced stage of HCC (IL-10, and MIP-3)." (PMID 41219858, 2025). "Therefore, GDF15 is closely involved in the progression of cancer." (PMID 40144214, 2025).
cancer (continued). "However, despite a growing body of research on the role of GDF15 and GDF11 in skeletal and cardiac muscle loss in cancer cachexia, the underlying mechanisms by which these growth differentiation factors facilitate muscle loss remain unknown." (PMID 40558549, 2025). "However, the precise role of the pro-NAG-1/GDF15 form in cancer remains largely unexplored." (PMID 40316530, 2025). "Under normal conditions, GDF15 (Growth Differentiation Factor 15) is expressed at low levels in most tissues; however, its expression significantly increases in pathological states such as tissue injury, inflammation, oxidative stress, and cancer, making it a potential biomarker in cancer patients." (PMID 41009755, 2025). "Notably, in large-scale screenings, GDF15 has been identified as the most significantly over-expressed soluble factor and its concentration is correlated with the progression in cancer patients across different cancer types, especially NSCLC." (PMID 40144214, 2025). "However, in a cancer model, GDF-15 blockade increased T-cell infiltration, promoting tumor control." (PMID 38686386, 2024). "Notably, EV-Growth and GDF15 from cancer cells emerge as key molecules in CC research." (PMID 38802952, 2024). "However, increased levels of GDF15 are found not only in primary mitochondrial disorders but also in different diseases like neurodegenerative diseases, cardiovascular diseases, and cancer." (PMID 38136224, 2023). "Interestingly, a recent study showed that Diltiazem, a calcium channel blocker, was able to prevent EMT and reduce migration and invasion of TNBC cancer cells by up-regulating GDF15, with GDF15 itself having the similar inhibitory effect on invasiveness and EMT." (PMID 37333824, 2023). "Notably, serum GDF15 levels in the TRACERx cohort (median age 70 years) were higher than previously published in age-matched non-cancer volunteers (60-70 years, median plasma GDF15 levels of 866 pg/ml) and in keeping with previous reports of increased circulating GDF15 in patients with NSCLC 46–49." (PMID 37045997, 2023). "However, it remains unknown if transcription of GDF15 relies on BRD4 throughout different cancer cell types." (PMID 37495707, 2023). "Moreover, it showed EV-mediated GDF-15 release by cancer cells worthy of follow-up study." (PMID 38069076, 2023). "However, as a member of TGF-β superfamily, there are still few reports on the role of GDF15 in tumor radioresistance, but more studies about the roles of GDF15 focus on its adverse effect on cancer cachexia, the regulation of immune microenvironments, and diagnostic marker of multiple solid tumors." (PMID 36142823, 2022). "Thus, tumor-derived GDF15 induces lipolytic activity and likely contributes to cancer cachexia." (PMID 35646636, 2022). "Moreover, since its expression levels are gradually increasing during the cancer progression, GDF15 may serve as a prognostic and predictive marker in cancer patients." (PMID 35694408, 2022). "Notably, GDF-15 had been reported to play roles in cancer cachexia." (PMID 35379793, 2022). "Indeed, Mendelian Randomization studies have shown that some of our biomarkers (GDF-15, cystatin-C) were not causally associated with cancer and CVD risks, respectively." (PMID 34935094, 2022). "We examined the associations between five markers of unhealthy ageing; Growth Differentiation Factor-15 (GDF-15), N-terminal pro-brain natriuretic peptide (NT-proBNP), glycated hemoglobin A1c (HbA1C), C-Reactive Protein (CRP) and cystatin-C; with risks of cancer and cardiovascular disease (CVD)." (PMID 34935094, 2022). "Notably, HIF-1 induces the expression of GDF15 in cancer metastasis." (PMID 36140453, 2022). "However, the exact role of GDF-15 within tumorigenesis is still unclear, with some evidence supporting its action in promoting malignancy, while others showing its inhibitory effects on cancer." (PMID 35872912, 2022). "Although GDF15 has been well characterized, its role in cancer progression remains unclear." (PMID 35280749, 2022).
cancer (continued). "Interestingly, the body weight lowering effect of GDF15 could be dissociated from its anorectic effect in a cancer model characterized by high GDF15 levels." (PMID 34831213, 2021). "In analyses of a subgroup with low BMI (<22.5 kg/m2), patients with elevated GDF-15 had 4.79-fold increased risk of cancer death and 11-fold greater risk of CV death when compared with patients with non-elevated GDF-15 (<1,200 ng/L) after adjustment for established risk factors." (PMID 34150865, 2021). "However, controversy exists regarding the role of GDF-15 in cancer development and progression, which may depend on the tumor type and study model." (PMID 33850096, 2021). "Accordingly, IGFBP7 and GDF-15, two molecules found to be related with cancer and not only with cardiovascular disease states, in the PREDICTOR cohort were found to predict not only all-cause mortality, but also the probability of cancer death after full adjustments." (PMID 34217226, 2021). "Interestingly however, with aging TRAMP mice overexpressing GDF15 develop more metastases than the other genotype TRAMP mice, suggesting that GDF15 may play a dual role in cancer." (PMID 32502202, 2020). "For example, altered food intake, reduced adiposity and accompanying changes in systemic metabolism could explain some of the protection from cancer seen in mice with overexpression of GDF15 and would be entirely coherent with GDF15 action via the hindbrain-restricted receptor GFRAL." (PMID 32310257, 2020). "Finally, the emerging role of GDF-15 as a target for future cancer therapies is outlined." (PMID 32508832, 2020). "This study also discovered that GDF15-knockdown (GDF15-KD) tumors had less stromal component and had different repertoires of activated and inhibited canonical pathways in the stromal cell and cancer cell components from that of the control tumors after cisplatin treatment." (PMID 33086658, 2020). "However, in this scenario, p38 activation was the cause of GDF15 overexpression suggesting that a positive feedback between GDF15 and p38 may exist that could drive drug resistance and invasiveness in different cancer types." (PMID 32046099, 2020). "It seems possible that cancer-derived circulating IL6 or GDF15 may trigger the activation of BATs." (PMID 33182625, 2020). "Furthermore, the general association of GDF‐15 on prognosis in treatment‐naïve cancer patients has not been investigated yet." (PMID 31463975, 2019). "However, functional studies of the roles played by GDF15 in cancer is limited and controversial." (PMID 30542297, 2018). "In addition, depending on the cellular localization, GDF15 might perform different functions leading to divergent roles in cancer." (PMID 30542297, 2018). "Nevertheless, our combined results of hsa-miR-873-5p-mediated repression of luciferase and endogenous GDF15 expression in two different cell types suggest that miR-873-5p may represent a novel therapeutic target for the treatment of cancers that exhibit increased activity of the GDF15 gene." (PMID 28806401, 2017). "Moreover, expression levels of GDF15 were heterogeneous among cancer cells." (PMID 28206960, 2017). "Further investigations regarding the interactions between the studied miRNAs and GDF15 levels and their involvement in the progression of cardiovascular diseases and cancers should be interesting and may help to uncover novel therapies against related complications." (PMID 28806401, 2017). "We therefore investigated whether GDF15 has a role in the regulation of cancer stemness in HNC." (PMID 27903972, 2017). "The authors suggested that Gdf15 could generally function in inflammatory diseases and cancer." (PMID 27220464, 2016). "Finally, although the effect of GDF15 on fibroblast was analyzed using NIH3T3 mouse embryonic fibroblast in the current study, the verification study using cancer-associated fibroblast derived from cancer patients is required for the determination of GDF15 function in cancer microenvironment." (PMID 26892343, 2016).